TNF (tumor necrosis factor)
Diseases named in the same sentence as TNF in open-access papers (continued):
Sharing a sentence is not in itself a finding about the gene and the disease.
rheumatoid arthritis (continued). "Standard anti-TNF-α treatment employed in treating rheumatoid arthritis has been demonstrated to decrease levels of soluble endothelial adhesions molecules as well as improve arterial stiffness and endothelial functions." (PMID 33053859, 2020). "Extending these studies to primary cells, these lead compounds also reduced IL-6 and CXCL8 production by TNF stimulated fibroblast-like synoviocytes (FLS) from rheumatoid arthritis (RA) patients." (PMID 33390996, 2020). "Anti–TNF-α mAb therapy is commonly used in the treatment of many inflammatory conditions, including rheumatoid arthritis, inflammatory bowel disease, and psoriasis." (PMID 32321757, 2020). "Following the encouraging results gained in rheumatoid arthritis two female patients with rapidly progressive MS were treated intravenously with monoclonal anti-TNF antibody (cA2), now called infliximab." (PMID 33066433, 2020). "Serum and synovial fluid of patients with rheumatoid arthritis have high amounts of proinflammatory cytokines such as TNF-α, IL-1β, and IL-6." (PMID 32708317, 2020). "In our previous study, leucine-rich alpha-2 glycoprotein (LRG) was identified as an inflammatory biomarker through the semiquantitative proteomic analysis of sera in patients with rheumatoid arthritis before and after anti-tumor necrosis factor (TNF) therapy." (PMID 33211747, 2020). "There are numerous studies on inflammatory cytokines such as IL-1α, IL-1β, and TNF-α in joint disorders, including osteoarthritis, rheumatoid arthritis, posttraumatic osteoarthritis, and hemophilic arthropathy." (PMID 33213419, 2020). "Little is known of the unclassified Turicibacter species; however, Turicibacteriaceae are decreased in mice that lack the pro-inflammatory cytokine TNF-α and increased in humans with rheumatoid arthritis." (PMID 32454449, 2020). "Curcumin, another inhibitor of mTOR signaling, was also reported to alleviate rheumatoid arthritis-induced inflammation and synovial hyperplasia by reducing inflammatory mediators like IL-1β, TNF-α, MMP-1, and MMP-3." (PMID 32867828, 2020). "The mechanisms by which only some rheumatoid arthritis (RA) patients respond favorably to TNF blockade are still poorly characterized." (PMID 32843099, 2020). "In rheumatoid arthritis, TNF-α, Interleukin (IL)-1, IL-6, and IL-17 produced by synovial macrophages and T cells act on osteoblasts to promote RANKL expression." (PMID 32708317, 2020). "Human osteocyte-enriched cells were cultured with serum of active rheumatoid arthritis patients ex vivo, which increased IL-1β, TNF-α, SOST, and DKK1 gene expression levels." (PMID 32708317, 2020). "Studies on rheumatoid arthritis have shown that blocking TNF stops the cytokine cascade, decreasing the levels of adhesion molecules and vascular endothelial growth factor (VEGF) involved in the pathways of augmented vascular permeability." (PMID 32521760, 2020). "Additional highly enriched relevant pathways were rheumatoid arthritis, fat digestion and absorption, and TNF signaling pathway." (PMID 33198757, 2020). "The top three downregulated genes were related to the tumor necrosis factor (TNF) signaling pathway, Staphylococcus aureus infection, and rheumatoid arthritis signaling pathway." (PMID 33585448, 2020). "Due to its dominant pro-inflammatory effects, drugs that neutralize TNF were developed and are clinically used to treat inflammatory and autoimmune diseases, such as rheumatoid arthritis, inflammatory bowel disease and psoriasis." (PMID 32528961, 2020). "Biological therapies, including anti-TNF agents, are important in the treatment of various chronic inflammatory diseases, including psoriasis, rheumatoid arthritis or inflammatory bowel disease." (PMID 32711929, 2020). "Multiple anti-TNF antibodies and TNF soluble receptors have been approved for use in humans to block TNF-α activity, and are primarily used to treat autoinflammatory conditions, such as rheumatoid arthritis." (PMID 33552087, 2020).
rheumatoid arthritis (continued). "The nanowhiskers solution in the PDT experiment on rats revealed an ameliorating effect on the rheumatoid arthritis by decreasing significantly the IL-17 and TNF-α level in blood serum." (PMID 32102185, 2020). "Our objective was to explore these access barriers for tumor necrosis factor (TNF) alpha inhibitors in rheumatoid arthritis (RA) in five Central and Eastern European countries." (PMID 32581804, 2020). "The other pathways were mainly enriched in immune signaling, including the TNF signaling pathway, staphylococcus aureus infection, rheumatoid arthritis, leukocyte transendothelial migration, and chemical carcinogenesis." (PMID 33014868, 2020). "We are reporting three patients with longstanding rheumatoid arthritis (RA), which developed IgAN while receiving TNF-alpha inhibitors." (PMID 32373375, 2020). "Therapeutic targeting of the pro-inflammatory cytokine TNFα was introduced as an efficient strategy to treat patients with autoimmune disorders such as rheumatoid arthritis and inflammatory bowel disease." (PMID 32864098, 2020). "For example, TNF-α is an inflammatory cytokine that is involved in multiple diseases such as rheumatoid arthritis, Crohn’s disease, and psoriasis." (PMID 33322533, 2020). "Anti-TNF therapeutics have long been used for the treatment of chronic inflammatory conditions, such as rheumatoid arthritis, psoriatic arthritis, plaque psoriasis, and Crohn’s disease." (PMID 33080861, 2020). "These three cytokines were selected because they are widely involved in the pathophysiology of several arthritis including rheumatoid arthritis; pathology in which IL‐1, IL‐6 and TNF‐α are therapeutic targets." (PMID 33159500, 2020). "For example, Th17 cells can infiltrate tissues and secrete proinflammatory TNF-α and GM-CSF, which exacerbate the pathogenesis of rheumatoid arthritis (RA), multiple sclerosis (MS) and other autoimmune diseases." (PMID 33552056, 2020). "The use of TNF-α antagonists has been associated with a decreased risk of myocardial infarction and development of acute coronary syndrome pointing to anti-TNF-α treatment as an effective anti-atherosclerotic therapy in rheumatoid arthritis." (PMID 33053859, 2020). "The gene TNF (tumour necrosis factor) is expressed in the myocardium in response to mechanical overload or ischaemic injury, while inhibition therapy of TNF may reduce the risk of myocardial infarction in patients with rheumatoid arthritis, a typically high risk group." (PMID 31845988, 2020). "In order to control for the efficacy of anti-TNF for the original application, to minimize the rheumatoid arthritis induced inflammation burden, various parameters can be measured." (PMID 33193432, 2020). "The infusion of TNFα worsened endothelial function in type II diabetic mellitus, and the inhibition of TNFα was able to improve endothelial function in the patients with rheumatoid arthritis." (PMID 32190663, 2020). "Aberrant tumor necrosis factor (TNF) signaling is a key pathogenic player in multiple chronic inflammatory diseases, including rheumatoid arthritis, lupus nephritis, and bacterial infection (sepsis)." (PMID 33585287, 2020). "In patients with rheumatoid arthritis, autophagy is activated by TNF-α, which induces osteoclast-mediated bone resorption." (PMID 33289699, 2020). "TNF blockade is also protective in collagen-induced and anti-collagen antibody-induced arthritis models, and this is consistent with the clinical benefit of TNF blockade in rheumatoid arthritis patients." (PMID 32671059, 2020). "Adalimumab is an antibody (IgG) that binds specifically to an inflammatory cytokine, human TNFα, and the antibody has been used in the therapy of the chronic inflammatory diseases including rheumatoid arthritis." (PMID 32514366, 2020). "For example, blockade of tumor necrosis factor (TNF) has shown positive results in Rheumatoid Arthritis and Crohn's disease." (PMID 33123148, 2020).
rheumatoid arthritis (continued). "TNF‐blockade has shown clear therapeutic value in rheumatoid arthritis and other immune‐mediated inflammatory diseases, however its mechanism of action is not fully elucidated." (PMID 31722123, 2020). "Rheumatoid arthritis patients had significantly higher TNF-α concentration in plasma (1.65 [1.2-2.42] pg/mL) than controls (0.99 [0.77-1.35] pg/mL, P < 0.001)." (PMID 33410302, 2020). "As a counterpoint, cytokine‐based clinical applications have been successful in cases where the clinical entity treated and the variables used to measure outcome were well defined, such as with anti‐TNFα for Rheumatoid Arthritis." (PMID 32336016, 2020). "As such, anti-TNF agents have become cornerstone in the treatment of autoimmune inflammatory conditions such as rheumatoid arthritis and inflammatory bowel disease." (PMID 32805626, 2020). "In conclusion, this systematic review reveals that anti-TNF treatment is therefore not only beneficial for rheumatic joints but also for the gums of rheumatoid arthritis patients." (PMID 33193432, 2020). "Treatment of synoviocytes from patients with rheumatoid arthritis with either recombinant IL-17A or IL-17F, in the presence of TNF, has been shown to induce a qualitatively similar gene signature." (PMID 32973785, 2020). "Cytokine-targeting therapies have been successfully used in the management of numerous chronic inflammatory diseases ever since TNF-neutralizing antibodies were deployed to treat rheumatoid arthritis (RA) in the 1990s." (PMID 33334075, 2020). "Tumor necrosis factor-α (TNF-α) is a key cytokine in inducing bone resorption in rheumatoid arthritis." (PMID 32046264, 2020). "Golimumab is a fully humanized anti-TNFα monoclonal antibody that is approved for the treatment of rheumatoid arthritis, psoriatic arthritis, ankylosing spondylitis, and moderate to severe ulcerative colitis, but not for JIA-U." (PMID 32293465, 2020). "Patient access barriers to TNF alpha inhibitors in rheumatoid arthritis, mentioned by at least in one interview in a country." (PMID 32581804, 2020). "Transfection of miR-20a mimic reduced the release of IL-6, CXCL10, and IL-1β, as well as TNF-α by rheumatoid arthritis fibroblast-like synoviocytes." (PMID 33584204, 2020). "Modulation of inflammatory mediators is a clinical reality: TNF-α antagonists have been used for years in ankylosing spondylitis and rheumatoid arthritis with good results, including slowing of the spinal manifestations of these diseases." (PMID 31986181, 2020). "These genes were mainly involved in pathways including NOD-like receptor signalling pathways, cytokine-cytokine receptor interactions, TNF-signalling pathway, Rheumatoid arthritis, and the NF-kappa B-signalling pathway." (PMID 31899762, 2020). "Consecutively, etanercept, a TNFα-inhibitor, has been successfully used in the treatment of rheumatoid arthritis and other chronic inflammatory diseases." (PMID 33334368, 2020). "This study aimed to directly analyze the potential relationship of anti-nuclear antibodies (ANA) before and after the administration of TNF-α inhibitors (TNFi) with the appearance of anti-drug antibodies (ADrA) in patients with rheumatoid arthritis (RA)." (PMID 33315881, 2020). "This literature review presents an overview of the possibly beneficiary effect of TNF inhibitors used in rheumatoid arthritis on periodontal parameters, with special emphasis on which parameters improve over time." (PMID 33193432, 2020). "Direct vagal nerve stimulation is known to reduce the proinflammatory response of cytokines including TNF-α and chemokines effectively in healthy individuals and in rheumatoid arthritis." (PMID 32908447, 2020). "In patients with rheumatoid arthritis, vitamin B6 supplementation improved pro‐inflammatory responses by suppressing TNF‐α and IL‐6 levels." (PMID 32967056, 2020). "Another study revealed that TREM2 inhibited the activation of TNF-α-induced inflammation response in rheumatoid arthritis via the p38 pathway." (PMID 32617097, 2020).
rheumatoid arthritis (continued). "A range of biologics targeting TNFα have been licensed for the treatment of various inflammatory diseases, such as rheumatoid arthritis and Crohn’s disease." (PMID 32093030, 2020). "Exposure of human macrophages to IgG-ICs in conjunction with TLR ligands amplifies production of TNF-α, IL-1β, and IL-6, all of which play critical roles in the pathology of diseases such as rheumatoid arthritis (RA)." (PMID 32719679, 2020). "Complement-mediated lysis of effector T cells that expressed surface TNF-α, described in rheumatoid arthritis and ankylosing spondylitis patients, is unlikely playing a role in our model for our protocol uses de-complemented human serum." (PMID 32069329, 2020). "Differing local and systemic inflammatory burden in polyarticular psoriatic arthritis and rheumatoid arthritis patients on anti-TNF treatment in clinical remission." (PMID 33195301, 2020). "Red cell distribution width is positively correlated with tumor necrosis factor alpha (TNF‐alpha) and interleukin (IL)‐6 in rheumatoid arthritis, suggesting that RDW is a potential adjunct marker that reflects an inflammatory process." (PMID 32196750, 2020). "A prior study compared retention rates following TNFα inhibitor treatment (etanercept, infliximab, and adalimumab) in rheumatoid arthritis, psoriatic arthritis and AS, and found the cumulative survival to favor AS patients." (PMID 32725789, 2020). "Therapeutic antibodies against the important pro-inflammatory cytokine TNF-α were approved already in the 1990s for use in rheumatoid arthritis (RA)." (PMID 31903161, 2020). "The application of conjunctival goblet cell count as a clinical biomarker to diagnose and respond to treatment can take place in rheumatoid arthritis patients under TNF-inhibitors (TNFi) therapy." (PMID 32820183, 2020). "In rheumatoid arthritis (RA), TNF‐α decreased the expression of Foxp3, which down‐regulated the suppressive function of Tregs." (PMID 32881301, 2020). "While some authors mention a concomitant diminished CD3ε and TCRζ expression in rheumatoid arthritis, in response to TNF, in murine models of cancer, or in inflamed tissues, some others do not." (PMID 33354577, 2020). "TNF-α central role in the pathogenesis of chronic autoimmune diseases like rheumatoid arthritis (RA), psoriasis and Crohn’s disease has led to the development of anti-TNF-α therapeutics widely used in the treatment of autoimmune diseases." (PMID 32457323, 2020). "TNF plays a key role in immune-mediated inflammatory diseases including rheumatoid arthritis (RA) and spondyloarthritis (SpA)." (PMID 32662821, 2020). "Infliximab (IFX) was the first anti-tumor necrosis factor (TNFα) antibody to be used in the treatment of severe chronic inflammatory diseases, such as Crohn’s disease and rheumatoid arthritis." (PMID 32390850, 2020). "This novel concept, in which TNF initiates a cascade of cytokine production, designated TNF as an interesting target for the treatment of inflammatory diseases like rheumatoid arthritis." (PMID 32174918, 2020). "Stigmasterol can decrease the levels of IL-17, TNF-α, and IL-1β in rheumatoid arthritis, can significantly reduce the plantar edema induced by MSU crystals, and can reduce the serum UA levels in hyperuricemia mice by inhibiting liver XOD activity." (PMID 33149752, 2020). "TNF-α is a strong proinflammatory cytokine with multiple effects on different cell types and plays a major role in inflammatory diseases, such as rheumatoid arthritis." (PMID 33322533, 2020). "Current therapeutic options for SpA are limited compared with those for rheumatoid arthritis (RA), especially for axSpA, and mainly antibody-based, such as anti-tumor necrosis factor (TNF), anti-Interleukin (IL)-23 and anti-IL-17." (PMID 33193430, 2020). "The use of a TNFα inhibitor (Etanercept), when combined with Methotrexate, were shown to reduce radiographic disease progression in those with rheumatoid arthritis despite high circulating inflammatory markers." (PMID 33584321, 2020).
rheumatoid arthritis (continued). "Synovial features of patients with rheumatoid arthritis and psoriatic arthritis in clinical and ultrasound remission differ under anti-TNF therapy: a clue to interpret different chances of relapse after clinical remission?" (PMID 33195301, 2020). "Inhibitors of tumor necrosis factor-α and antibodies against IL-1β have improved fatigue symptoms in patients with psoriasis, diabetes, and rheumatoid arthritis." (PMID 32809068, 2020). "In the past two decades, blockage of TNF-α has been clinically applied in the treatment of inflammatory diseases, including rheumatoid arthritis, multiple myeloma, and psoriatic arthritis, and remarkable therapeutic effects have been observed." (PMID 32183881, 2020). "Collectively, these inflammatory factors are mainly concentrated in rheumatoid arthritis, FoxO signaling pathway, toll-like receptor signaling pathway, and TNF signaling pathway, and aggravated the symptoms of DN to some extent." (PMID 32215271, 2020). "Cytokine blockade is currently being evaluated for efficacy in other inflammatory diseases, for example through targeting of the pro-inflammatory mediators IL-17 and tumor necrosis factor α (TNFα) in rheumatoid arthritis." (PMID 32397175, 2020). "When summarizing the findings of this study, the periodontal status of rheumatoid arthritis patients receiving anti-TNF administration benefitted from this treatment, especially when analyzed from 6 weeks up to 6 months after start of intervention." (PMID 33193432, 2020). "Targeting the inhibition of IL-6 by bLF has positive clinical implications, for instance for patients with rheumatoid arthritis that fail anti-TNF therapy." (PMID 32477333, 2020). "It was shown that IL1RN has beneficial effects in treating rheumatoid arthritis where the pro-inflammatory cytokine TNFα is a driver for the pathological progression." (PMID 32244522, 2020). "On the other hand, in agreement with the current study, paeonol decreased the TLR4/NF-κB/TNF-α/IL-6 inflammatory signaling pathway in lipopolysaccharide-induced acute lung injury and IL-1β-induced human fibroblast-like synoviocyte rheumatoid arthritis." (PMID 32104151, 2020). "In conditions such as rheumatoid arthritis, blockade of TNFα leads to a subsequent decrease in IL-1 and IL-6, adhesion molecules and angiogenic factors such as vascular endothelial growth factor (VEGF)." (PMID 32903555, 2020). "CB2 agonist 4Q3C showed an anti-inflammatory effect in rheumatoid arthritis mouse model (reduced bone erosion, inhibited formation of osteoclasts and lowered the level of TNFα, IL-1β, COX-2 and inducible NO synthase)." (PMID 33036283, 2020). "Infliximab, a TNF-α antibody that blocks TNF-α receptor interactions has shown promise in the treatment of rheumatoid arthritis, as has Etanercept, an agent that binds with TNF-α preventing from interacting with its receptor." (PMID 33584321, 2020). "These genes are mainly involved in pathways including NOD-like receptor signalling pathways, cytokine-cytokine receptor interactions, TNF-signalling pathway, Rheumatoid arthritis, and NF-kappa B-signalling pathway etc." (PMID 31899762, 2020). "In our two previous studies in rheumatoid arthritis (RA) and ankylosing spondylitis (AS), in which anti-TNF therapies are also highly beneficial, we found significant differences in the T-cell subset composition among responder and non-responder patients." (PMID 32248339, 2020). "Studies have confirmed that TNF-α is likely to be an upstream promoter in the process of rheumatoid arthritis inflammation." (PMID 32063980, 2020). "TNF inhibitors have been available for inflammatory diseases like rheumatoid arthritis, ankylosing spondylitis, psoriatic arthritis, psoriasis, ulcerative colitis and Crohn’s disease since 1998." (PMID 33193432, 2020).